PTH (parathyroid hormone)
Diseases named in the same sentence as PTH in open-access papers (continued):
Sharing a sentence is not in itself a finding about the gene and the disease.
anemia (continued). "With our patient and our single‐center data, there appears to be great variability in the relationship between PTH level and both anemia and bone marrow changes." (PMID 35846199, 2022). "Factors such as malnutrition, anemia, high PTH values, and lower solute clearance, as measured by urea Kt/V, have been correlated with this observation." (PMID 36547239, 2022). "In the group of patients without compression fractures these parameters were higher.In the subgroup of patients with total calcium concentration above 3 mmol/L and PTH above 3 normal values, the incidence of anemia reached 21% (95% CI: 10%; 35%)." (PMID 34766485, 2021). "Laboratory findings include increased PTH, Ca, P, alkaline phosphatase, creatinine, Ca × P product, and anemia." (PMID 32736815, 2020). "The reduction in mortality is likely related to myriad of metabolic improvements that result in favourable effects on cardiac function, including improvement in anemia, calcium-phosphate profile, reduction of parathyroid hormone, and neurohormones." (PMID 30554567, 2018). "Routine laboratory tests revealed a normochromic, normocytic anemia, normal fasting glucose and lipid panels, normal total and ionized calcium and normal levels of parathyroid hormone." (PMID 30393977, 2018). "Some cardiovascular risk factors in patients on dialysis include disorders of calcium-phosphate and parathyroid hormone, fluid volume overload, anemia, hyperkalemia, increased oxidative stress, and chronic inflammation." (PMID 28666408, 2017). "It is also proposed that it is likely that vitamin D improves anaemia only in those with very high PTH and marrow fibrosis." (PMID 27506667, 2016). "It has been suggested that vitamin D improves anaemia only in those with very high PTH levels and those with marrow fibrosis." (PMID 27506667, 2016). "The majority of anemic patients were found in the highest quartile of PTH whatever the level of hemoglobin used for the definition of anemia." (PMID 25113067, 2015). "It offers better phosphate, PTH, anemia and blood pressure control, fewer dietary restrictions, and removes the dangers of the long weekend." (PMID 24614569, 2014). "Patients with a higher AASI were older and had: worse renal function; more chronic CKD (anemia, higher serum levels of phosphate and parathyroid hormone); higher LVMI and cIMT; and higher BP." (PMID 24245955, 2013). "In this study, RBC showed a significant negative correlation with Ln_PTH in correlation analysis among non-dialysis patients, suggesting that intact PTH is associated with anemia in CKD5 patients." (PMID 39791168, 2025). "Intact PTH is a possible contributor to anemia in CKD patients." (PMID 39791168, 2025). "Given PTH’s impact on HSC, variations in PTH levels could affect erythrocyte production and may influence malaria-associated anemia severity." (PMID 39492784, 2024). "By understanding the specific relationship between anemia and PTH levels in HD patients, we have the potential to develop more targeted strategies for managing anemia, with the potential to prevent complications and improve treatment outcomes, especially in low-resource countries." (PMID 39109107, 2024). "Compared with a baseline before dialysis, anemia, low albumin, blood pressure, blood urea nitrogen, creatinine, uric acid, potassium, calcium, phosphorus, and parathyroid hormone improved after 6 and 12 months, while the residual renal function gradually decreased during the follow-up." (PMID 35180850, 2022). "Based on the findings with our patient and our institutional cohort, we suggest that it is justified to deviate from “on‐size‐fits‐all” protocols and attempt a trial of aggressive management of SHP in patients with difficult to manage ESA‐resistant anemia and more modest PTH elevation." (PMID 35846199, 2022).
anemia (continued). "In recent studies, ESS was reported to correlate with perioperative anemia and metabolic disorder of Vitamin D, as well as parathyroid hormone (PTH), which could increase the possibility of reoperation after hip fractures." (PMID 34470653, 2021). "The hypomagnesemia group showed significantly lower average hemoglobin levels than the normal magnesium group in both males and females, and the greater prevalence of anemia in the hypomagnesemia group persisted after controlling for the presence of eGFR and PTH." (PMID 34416890, 2021). "In addition to anemia, the uptake of dopaminergic neurons negatively correlated with the serum parathyroid hormone in our study." (PMID 32213981, 2020). "Therefore, in early as in advanced CKD, the clinical goal of vitamin D therapy is to increase 25-OH-D levels to normal in order to optimize control of proteinuria, anemia and PTH." (PMID 28726185, 2018). "Serum PTH was associated with anaemia in univariate but not multivariate analysis, presumably a reflection of its association with underlying allograft function." (PMID 30290796, 2018). "Yet the common symptoms include anemia, anorexia, malnutrition, disorders in the serum calcium levels, phosphorus and the regulating hormones of their hemostasis including parathyroid hormone (PTH), p 1.25 hydroxyvitamin D as well as disorders in sodium hemostasis, potassium, water and acid status." (PMID 28497080, 2017). "We first revealed that adipocytes produced more leptin through up-regulated Akt signaling because of normalization with high PTH environment, which in turn increased circulating leptin levels, and finally improved anemia and malnutrition in severe SHPT patients after PTX." (PMID 27307101, 2016). "The association between PTH and hemoglobin was independent of factors that are commonly related to anemia in dialysis patients; age, gender, iron status, biomarkers of inflammation and nutrition were, in fact, not predictors of hemoglobin concentration." (PMID 25113067, 2015). "In addition, the percentage of patients with anemia was always higher in patients in the highest quartile of PTH whatever the level of serum hemoglobin concentration used for the definition of anemia." (PMID 25113067, 2015). "Possible factors contributing to this general improvement include defined standards for adequate dialysis, increased attention to calcium, phosphate and PTH control, better anemia control, better preparation of dialysis initiation, and a tendency towards earlier dialysis initiation." (PMID 24614569, 2014). "Similarly, defective vesicle exocytosis can explain a failure in PTH secretion and a decremental pattern of muscle contractions in repetitive stimulation of the neuromuscular junction observed in Patient 1; however, severe anemia cannot be explained." (PMID 36645181, 2023). "Furthermore, the different results between relatively contemporaneous groups of patients may reflect referral patterns, such as unexplained anemia, bone fracture, and inappropriate bone turnover due to parathyroid hormone." (PMID 36190833, 2022). "Fourth, parathyroid hormone and fibroblast growth factor 23 might have a damaging effect on iron metabolism and confound the association between VD and iron circulation and anemia, but they were not measured in our study." (PMID 35745185, 2022). "The severe degree of anemia and transfusion dependence, despite a PTH of only 400.5 pg/ml, and the documented reversibility of the bone marrow fibrosis and achievement of transfusion independence with improvement of PTH levels highlight an important novel observation." (PMID 35846199, 2022). "Therefore, the lowering of plasma PTH may well explain the partial correction of anemia in rats receiving cinacalcet." (PMID 29078759, 2017).
anemia (continued). "Although the BMI Z scores of our dialysis subgroup were normal, other factors could have contributed to the reduction in functional exercise capacity, such as decreased height, anemia, a reduced renal glomerular filtration rate and a high parathyroid hormone level." (PMID 26872080, 2016). "Therefore, in addition to reducing PTH, reduction of fibroblast growth factor 23 may be one pathway through which cinacalcet improves anemia." (PMID 27764168, 2016). "In our fully adjusted model, the magnitude of the effect of anemia on total FGF23 was similar to that of eGFR, and was greater than that of phosphate SDS for age, serum PTH, and active vitamin D use." (PMID 37752381, 2024). "In addition, parathyroid hormone (PTH) inhibits erythropoiesis and promotes osmotic fragility of erythrocytes through calcium-ATPase stimulation; thus, it is conceivable that high-phosphate levels may have promoted PTH secretion and affected anemia." (PMID 37605118, 2023). "In addition, high PTH levels may play a role in anemia in PHPT patients." (PMID 34873402, 2021). "Laboratory investigation revealed an increase in P, Ca, parathyroid hormone (PTH), and alkaline phosphatase, as well as anemia and hypoalbuminemia." (PMID 32736815, 2020). "Elevated levels of phosphate, PTH, FGF-23, AGEs and uremic toxins, but also anemia and proteinuria can induce a systemic pro-inflammatory state." (PMID 31551803, 2019). "In summary, the present systematic review of published RCTs suggested that FC reduces serum phosphate, i-PTH, and FGF-23 levels and improves anemia-related parameters, namely Hb, TSAT, and ferritin in patients with CKD stage 3–5D." (PMID 29291028, 2017). "Together with inflammation, elevated levels of parathyroid hormone (PTH), lower levels of vitamin D, and anemia, all common features of CKD, have been recognized as proangiogenic stimuli." (PMID 28133420, 2017). "Considering the positive correlation between the serum FGF-23 levels and PTH, FGF-23 is believed to contribute to the development of anemia in dialysis patients." (PMID 25295189, 2014). "Therefore, the rationale of our study is to evaluate the prevalence of anemia in ESRD-undergoing MHD patients and the correlation between serum Hb levels with raised intact PTH (iPTH > 300 pg/mL) levels and other factors." (PMID 36815007, 2023). "While the literature does seem to indicate that there is a strong relationship between SHP and ESA‐resistant anemia, treatment of SHP is primarily dictated by goals in PTH, vitamin D, calcium, and phosphorus levels; even these goals that dictate clinical practice are not always scientifically based." (PMID 35846199, 2022). "The great variability in PTH levels of both affected and unaffected patients (i.e., bone marrow fibrosis and/or remodeling) indicates the relationship between SHP and ESA‐resistant anemia is complex and likely unique for each patient." (PMID 35846199, 2022). "No guidelines currently exist on PTH goals in the treatment of SHP when targeting improvement in ESA‐resistant anemia." (PMID 35846199, 2022). "Furthermore, the findings from our review of all bone marrow biopsies for patients with anemia and ESRD over a 10‐year period at our institution reveal a greatly variable range of PTH levels at which patients display bone marrow changes." (PMID 35846199, 2022). "However, the ideal PTH level in ESA‐resistant anemia has not been determined and likely vary from subject to subject." (PMID 35846199, 2022). "The development of left ventricular hypertrophy (LVH) involves classic factors suchas anemia, changes in renin-angiotensin-aldosterone system (RAAS), and hypertensionin addition to the independent mechanisms from the mTOR, phosphorus, and parathyroidhormone (PTH)." (PMID 29738042, 2018). "Cinacalcet is also likely to participate in improving anemia via pathways not driven by PTH levels." (PMID 27764168, 2016).
anemia (continued). "A potential contributor to anemia could be the renal osteodystrophy seen in ESRD patients, in which the elevation of circulating phosphate produces decreased levels of calcium and subsequent elevated parathyroid hormone (PTH)." (PMID 26445018, 2015). "In conclusion, our study shows for the first time that paricalcitol, compared to calcitriol, exerts a beneficial effect on Hb levels in patients with advanced CKD independent of several confounding factors involved in anemia pathogenesis, like inflammation and PTH levels." (PMID 25781618, 2015). "In fact, we are aware that PTH may have several extra-mineral negative effects in dialysis patients, spanning from increased left ventricular hypertrophy and higher blood pressure to erythropoietin-resistant anemia and poor nutrition and quality of life." (PMID 37351832, 2023). "Therefore, the impact of i-PTH elevation on anemia was not confirmed in the present study." (PMID 28475601, 2017). "Subjects with anemia had higher EPO, iFGF23, CRP, and phosphate and lower eGFR, while we were not able to show statistical difference regarding PTH, D vitamin, and calcium levels." (PMID 35739404, 2022). "In our trial, hemoglobin levels and iron indices, as well as serum calcium, phosphate, and parathyroid hormone concentrations, remained essentially identical in the Theranova and Revaclear arms, indicating no impact of MCO versus HF membranes on anemia management or mineral bone parameters." (PMID 41464753, 2025). "This was a post-hoc analysis based on a randomized, controlled study in which data was collected with the primary aim of assessing the modifying effect of nutritional VD on PTH levels and the protocol was not adapted to assess an effect of VD on HEP-25 and anemia." (PMID 36698076, 2023). "FGF23 is regulated at the transcriptional and posttranscriptional levels by several bone mineral factors, including phosphate (via glycerol-3-phosphate and lysophosphatidic acid), calcium, vitamin D, and parathyroid hormone (PTH), and nonmineral factors like anemia, inflammation, and metabolism." (PMID 37681408, 2023).
pseudohypoparathyroidism (123 papers, 2002 to 2026). "Pseudohypoparathyroidism (PHP) is a group of rare endocrine disorders caused by end-organ resistance to parathyroid hormone (PTH)." (PMID 41170251, 2025). "This condition is commonly associated with type 1A and 1C pseudohypoparathyroidism and pseudo-pseudohypoparathyroidism due to resistance of parathyroid hormone." (PMID 38558694, 2024). "Genetic and/or epigenetic defects determining a partial deficiency of Gsα lead to resistance to the action of the PTH hormone, which is the hallmark of pseudohypoparathyroidism (PHP), and the alteration of the PTH/PTHrP-Gsα-cAMP signaling pathway." (PMID 38828417, 2024). "Pseudohypoparathyroidism (PHP) is one of those disorders characterized by resistance to parathyroid hormone (PTH) and several other hormones that is caused by genetic alterations that impair the expression or function of Gsα." (PMID 38290008, 2024). "PTH-dependent hyperphosphatemic disorders include pseudohypoparathyroidism, where PTH resistance causes a decrease of 1,25(OH)2D3 and an increase in serum FGF23 concentration." (PMID 35084563, 2022). "Mutations and/or epigenetic changes in the Gnas transcript are implicated in pseudohypoparathyroidism (PHP) which is characterized by resistance to parathyroid hormone (PTH) and developmental abnormalities." (PMID 31947640, 2020). "Pseudohypoparathyroidism type 1a (Albright's hereditary osteodystrophy) due to GNAS mutations involves generalized hormone resistance (PTH, TSH, FSH, and LH), short stature, and various skeletal anomalies." (PMID 31320908, 2019). "Pseudohypoparathyroidism (PHP) is a rare endocrine disease characterized by resistance to the action of the parathyroid hormone (PTH), which is divided into PHP1 caused by (epi)genetic defects of GNAS gene which encodes stimulatory guanine nucleotide-binding protein (Gsα)." (PMID 36465610, 2022). "Pseudohypoparathyroidism is a condition associated primarily with resistance to the parathyroid hormone and the term Pseudopseudohypoparathyroidism is used to describe a condition where the individual has the phenotypic appearance of Pseudohypoparathyroidism type 1a, but is biochemically normal." (PMID 24098952, 2013). "Moreover, hypoprolactinemia has been described in patients with hemochromatosis and in patients with pseudohypoparathyroidism, a rare genetic disorder characterized by a resistance to parathyroid hormone (PTH) caused by GNAS (guanine nucleotide binding protein, alpha stimulating) mutations." (PMID 36967769, 2023). "Maternal inactivating GNAS mutations lead to pseudohypoparathyroidism 1A (PHP1A), newly classified as inactivating parathyroid hormone (PTH)/PTHrP-signaling disorder type 2 of maternal inheritance (iPPSD2)." (PMID 37440712, 2023). "Pseudohypoparathyroidism (PHP) is an uncommon endocrine condition marked by an impaired response to parathyroid hormone (PTH), which results in biochemical abnormalities." (PMID 40125101, 2025). "Pseudohypoparathyroidism (PHP) is a rare hereditary disorder that impairs the ability to respond to parathyroid hormone (PTH), even when the hormone levels are in the normal range." (PMID 40125101, 2025). "Pseudohypoparathyroidism (PHP) is a metabolic disorder that occurs due to target end-organ resistance to parathyroid hormone (PTH)." (PMID 41322012, 2025). "Pseudohypoparathyroidism (PHP) is a rare genetically determined disease with a wide range of symptoms related to target organs’ resistance to parathyroid hormone (PTH)." (PMID 40444234, 2025). "Pseudohypoparathyroidism (PHP) is a rare endocrine disorder marked by the body's resistance to parathyroid hormone (PTH)." (PMID 41555976, 2025). "In 2016, the European Pseudohypoparathyroidism Network (EuroPHP) network proposed a broader classification, ‘inactivating PTH/PTHrP signaling disorder (iPPSD)’ to unify PHP and other related conditions." (PMID 41170251, 2025).